CTIF (cap binding complex dependent translation initiation factor)
Description:
Specifically required for the pioneer round of mRNA translation mediated by the cap-binding complex (CBC), that takes place during or right after mRNA export via the nuclear pore complex (NPC). Acts via its interaction with the NCBP1/CBP80 component of the CBC complex and recruits the 40S small subunit of the ribosome via eIF3. In contrast, it is not involved in steady state translation, that takes place when the CBC complex is replaced by cytoplasmic cap-binding protein eIF4E. Also required for nonsense-mediated mRNA decay (NMD), the pioneer round of mRNA translation mediated by the cap-binding complex playing a central role in nonsense-mediated mRNA decay (NMD).
Synonyms: KIAA0427; Gm672
Tractability: PROTAC: its protein half-life has been measured.
Gene: Protein-coding gene on chromosome 18 (48,539,005 to 48,863,217, forward strand). Ensembl gene ENSG00000134030.
Subcellular location: Cytoplasm, perinuclear region
Subcellular location (Human Protein Atlas): Cytosol
Gene Ontology:
Molecular function: protein binding; translation activator activity; RNA binding
Biological process: nuclear-transcribed mRNA catabolic process, nonsense-mediated decay; regulation of translational initiation; positive regulation of translation
Cellular component: cytosol; perinuclear region of cytoplasm
Genetic constraint (gnomAD): Loss-of-function variants: 21 observed, 62.14 expected, observed/expected ratio (o/e) 0.34, 90% interval 0.24 to 0.49. The upper end of that interval is the gene's LOEUF score, 0.49, which puts it in group 2 of 6, group 1 being the genes least tolerant of losing a copy. Missense variants: 739 observed, 826.48 expected, observed/expected ratio (o/e) 0.89, 90% interval 0.84 to 0.95. Synonymous variants: 345 observed, 334.47 expected, observed/expected ratio (o/e) 1.03, 90% interval 0.94 to 1.13.
Homologues: Orthologues: chimpanzee CTIF (99% identical), dog CTIF (96% identical), pig CTIF (95% identical), mouse Ctif (93% identical), rat Ctif (93% identical), guinea pig CTIF (93% identical), macaque CTIF (91% identical), rabbit CTIF (81% identical), tropical clawed frog ctif (70% identical), zebrafish ctif (66% identical), Drosophila melanogaster CG13124 (14% identical), Caenorhabditis elegans F44A2.5 (10% identical). Paralogues in human: PAIP1 (14% identical), MIF4GD (12% identical).
Diseases named in the same sentence as CTIF in open-access papers:
CTIF is named in the same sentence as 14 diseases in open-access papers, as found by Europe PMC text mining. Sharing a sentence is not in itself a finding about the gene and the disease. The quoted sentences say what the papers report.
amyotrophic lateral sclerosis (2 papers, 2017 to 2021). Amyotrophic lateral sclerosis (ALS) is a neurodegenerative disease characterized by progressive muscular paralysis reflecting degeneration of motor neurons in the primary motor cortex, corticospinal tracts, brainstem and spinal cord. "CTIF also shares a domain with inclusion bodies containing the SOD1 mutant G93A, which is a histologic feature of amyotrophic lateral sclerosis; thus, CTIF may be related to occurrence and development of this disease." (PMID 34239534, 2021).
cervical cancer (1 paper, 2021). A primary or metastatic malignant neoplasm involving the cervix. "The result shows that POLR2J2, RBFOX3, RBMS1, ADARB1, AFF3, CSDC2 and CTIF were down-regulated in most of cervical cancer tissues compared with corresponding normal cervix tissues." (PMID 34863153, 2021).
hearing loss (1 paper, 2023). "CTIF is a component of the translation initiation complex involved in protein translation and an SNP within the CTIF gene is associated with hearing loss." (PMID 38076560, 2023).
lung adenocarcinoma (1 paper, 2014). A carcinoma that arises from the lung and is characterized by the presence of malignant glandular epithelial cells. "Among them, only three genes (CTIF, FAU, and RPS28) are significantly down-regulated in tumors, implying NMD may not be inhibited in lung adenocarcinoma and thus cannot explain the large amount of intron retentions in tumors." (PMID 24646369, 2014).
migraine (1 paper, 2023). "In addition, he had a rare variant in another migraine-associated gene, CTIF c.1547A>G (p.(Gln516Arg))." (PMID 37107589, 2023). "The resulting subnetwork included 9 genes: migraine-associated genes APOE, LRP1, CARF, CTIF, RNF213, and ECM1; LAMA2, which is associated with vestibular anomalies in mice; and the neurodevelopment-associated genes MYO5A and KLC2." (PMID 37107589, 2023). "The majority of the identified variants were found in genes previously associated with migraine (LRP1, ECM1, CARF, CTIF, RNF213, APOE, SLC35D2), with two different rare LRP1 variants each identified in two unrelated children with vertigo." (PMID 37107589, 2023).
neurodegenerative disease (2 papers, 2017 to 2020). A disorder of the central nervous system characterized by gradual and progressive loss of neural tissue and neurologic function. "Therefore, our results, which indicated the important role of CED complex in aggresome formation, led us to examine whether CTIF is enriched in the intracellular inclusion bodies of neurodegenerative diseases." (PMID 28589942, 2017).
tumor (1 paper, 2023). "Lastly, the EHD2, CTIF, FBXO32, PIP5K1C, and AHNAK genes were found to be co-expressed in the adjacent healthy tissue and tumor tissue groups." (PMID 37365287, 2023).
CTIF also shares sentences with these, for which no sentence is quoted: cancer (1 paper); epilepsy (1); glioma (1); lung carcinoma (1); mesothelioma (1); pulmonary fibrosis (1); Vertigo (1).